CD4 (CD4 molecule)
Diseases named in the same sentence as CD4 in open-access papers (continued):
Sharing a sentence is not in itself a finding about the gene and the disease.
ischemic stroke (continued). "In particular, cytotoxic CD8+ lymphocytes have been detected in the ischemic brain within 3 hours after ischemic stroke, whereas CD4+ T cells and natural killer cells are recruited during the first 24 hours and peak at 72 hours after reperfusion." (PMID 35309326, 2022). "CD4+ and CD8+ T cells contribute to the inflammatory and thrombogenic responses, brain damage, and neurological deficits associated with experimental ischemic stroke." (PMID 35309326, 2022). "The level of IL-21 in the brain is increased after ischemic stroke with infiltrated CD4+ T cells being its major source." (PMID 34335623, 2021). "In our experimental conditions, flow cytometry analysis reveals a significant reduction of CD73 in total lymphocytes from ischemic stroke patients in comparison to control subjects, findings that were also confirmed in CD4+ and CD8+T-cell subsets." (PMID 32344922, 2020). "Percentage of CD39+ among CD4+ lymphocytes was equal to 8.56% ± 0.74% and to 11.35% ± 1.29% in healthy controls and ischemic stroke patients, respectively (p = 0.13)." (PMID 32344922, 2020). "The frequency of CD4+ was equal to 48.45% ± 1.65% and 51.32% ± 2.30% in controls and ischemic stroke patients, respectively (p = 0.18)." (PMID 32344922, 2020). "The difference in the frequency of CD73+ cells between healthy subjects and ischemic stroke patients was significant, within the CD4+ population, with values of 2.96% ± 0.45% and 1.47% ± 0.25%, respectively (p = 0.0315)." (PMID 32344922, 2020). "Ischemic stroke increases the percentage of alveolar macrophages, neutrophils, and CD11b+ dendritic cells, but reduces the percentage of CD4+ T cells, CD8+ T cells, B cells, natural killer cells, and eosinophils in the lungs." (PMID 31691533, 2019). "In this study, we investigated the effects of CD4 T cell deficits on oxidative stress and on the Akt/mTOR cell signaling pathways after ischemic stroke in mice." (PMID 32832192, 2018). "T lymphocytes enter the brain by 24 h after ischemic stroke, and both CD4+ and CD8+ T cells contribute to post-ischemic injury in mice." (PMID 25477780, 2014). "Notably, CD39 on CD39+ activated CD4 Tregs emerges as a pivotal immune element for neuroprotection in ischemic stroke." (PMID 38323746, 2024). "Notably, we highlight the significance of CD39 on activated CD4 Tregs as an essential immune element for neuroprotection during ischemic stroke." (PMID 38894965, 2024). "In addition, in ischemic strokes, emerging evidence has shown that CD4+ Tregs play a critical role in maintaining immune hemostasis and suppression of immune responses." (PMID 36142962, 2022). "The protective role of CD4+ Tregs in ischemic stroke has been widely reported." (PMID 35912857, 2022). "CD4- CD8- T cell count increases from day 1 to day 3 after ischemic stroke." (PMID 34335623, 2021). "Blood samples from 21 ischemic stroke patients and 20 healthy subjects were analyzed by flow cytometry to evaluate the frequency of CD4+ and CD8+ T cells in order to identify if there were differences in CD4/CD8 ratio in patients in comparison to healthy subjects." (PMID 32344922, 2020). "Moreover, a study showed that subsets of CD4 (+) T-helper cells in vivo are able to selectively express Pmch, which has been known to play a central role in the pathophysiology of ischemic stroke." (PMID 28061506, 2017). "Although ischemic stroke reduces the numbers of lymphocytes in the circulation and lymphoid organs, subjects with acute ischemic stroke had a significantly higher number of circulating CD4+ T cells in peripheral blood compared to control subjects without acute ischemic lesions." (PMID 40342517, 2025). "We noticed that neutrophils, activated memory CD4 T cells and M0 macrophages may be related to the initiation and progression of ischaemic stroke; however, naive CD4 T cells, resting mast cells, CD8 T cells and eosinophils play a protective role in ischaemic stroke." (PMID 35962388, 2022).
ischemic stroke (continued). "Indeed, BDNF positive Tregs are upregulated compared to other BDNF positive CD4+ T-cells in the human brain following ischemic stroke, suggesting that Tregs may influence oligodendrocyte differentiation via the BDNF pathway." (PMID 31010132, 2019). "Recent evidence indicates that in patients with ischaemic stroke, CD8+ and CD4+ T cells are activated in the cerebrospinal fluid, and T-cell migration and infiltration are guided by HLA molecule interactions." (PMID 38548806, 2024). "Notable disparities in plasma levels of CD3, CD4, CD19, and INF-γ emerge when comparing ischemic stroke subtypes, specifically lacunar infarction, with non-ischemic stroke subtypes." (PMID 38287458, 2024). "According to our analysis, ischemic stroke patients had reduced infiltration of naive B cells, CD8 T cells and naive CD4 T cells, while there was a trend towards increased infiltration of activated CD4 memory T cells, M0 macrophages and neutrophils." (PMID 38112574, 2023). "As early as 24 hours after middle cerebral artery occlusion (MCAO), a mouse model of ischemic stroke, there is an upregulation of CCR5 in CD4+ CD25+ Tregs." (PMID 34335623, 2021). "Glycyrrhizin (Gly) is thought to protect against brain damage induced by ischaemic stroke by inhibiting the activation of CD8+ and CD4+ T cells mediated by IFN and partly regulated by HMGB1 activity." (PMID 33461586, 2021). "The aim of the study is to assess the presence of ARs in lymphocytes from ischemic stroke patients compared to healthy subjects and to analyze changes in CD39 and CD73 expression in CD4+ and CD8+ lymphocytes." (PMID 32344922, 2020). "In flow cytometry experiments, the percentage of CD73+ cells was significantly decreased in lymphocytes and in T-lymphocyte subclasses CD4+ and CD8+ obtained from ischemic stroke patients in comparison with healthy individuals." (PMID 32344922, 2020). "T lymphocytes (CD3+ cells) are mostly comprised of CD4+ T helper (Th) and CD8+ cytotoxic T (Tc) cell subpopulations, both of which are thought to play detrimental roles in ischemic stroke." (PMID 25477780, 2014). "We next focused on investigating the influence of P2X7 on CD4+and CD8+T cells in ischemic stroke." (PMID 40948793, 2025). "These analyses underscore the distinctive characteristics of different GZMK+ T-cell subsets, emphasizing that CD8+ GZMK+ T cells, rather than CD4+ GZMK+ T cells, are associated with ischemic stroke and reperfusion." (PMID 40659887, 2025). "Similar to CD4+ T cells, CD8+ T cells are also profoundly activated after ischemic stroke, and the accumulation of CD8+ T cells peaks approximately 3–4 days after stroke onset, with cell numbers decreasing overtime, and of note many studies also showed its existence in the chronic phase." (PMID 38077952, 2023). "The CIBERSORT results revealed decreased infiltration of naive CD4 T cells, CD8 T cells, resting mast cells and eosinophils and increased infiltration of neutrophils, activated memory CD4 T cells and M0 macrophages in the ischaemic stroke patients." (PMID 35962388, 2022). "In addition, previous works suggested that CD3+CD4+ T cells, CD3+CD8a+ T cells, DNT cells, and γδ T cells exhibit diverse functions in ischemic stroke by regulating immunological and inflammatory homeostasis." (PMID 34262436, 2021). "Mild increases in neutrophils (p = 0.045) and decreases in the total number of lymphocytes (p = 0.03) were present in the ischemic stroke patients, while CD4+ and CD8+ T cells were non-significantly reduced and monocyte counts were unaltered (p = 0.99)." (PMID 24840735, 2014). "CD4 + T cells can also serve as negative modulators of neurogenesis after ischemic stroke." (PMID 41146571, 2025). "Furthermore, CD39 phenotype immune cells, particularly CD39+ CD8+ T cells (inverse variance weighting [IVW] OR 0.92, 95% CI 0.87–0.97; p = 0.002) and CD39+ activated CD4 regulatory T cells (IVW OR 0.93, 95% CI 0.90–0.97; p < 0.001), show notable neuroprotection against ischemic stroke." (PMID 38323746, 2024).
ischemic stroke (continued). "The CIBERSORT results suggested that there was a decreased infiltration of naive CD4 T cells, CD8 T cells, resting mast cells and eosinophils and an increased infiltration of neutrophils, M0 macrophages and activated memory CD4 T cells in ischaemic stroke patients." (PMID 35962388, 2022). "Additionally, there was no infiltration of CD4+ T cells in Rag-/- OTII transgenic mice on day 14 after ischemic stroke." (PMID 34335623, 2021). "It has suggested that gut-derived CD4+ T cells may interact with meningeal macrophages and result in non-gut-derived CD4+ T lymphocyte infiltration into the brain in ischemic stroke." (PMID 32047521, 2020). "High concentration of anti-CMV IgG was associated with ischaemic stroke in the univariable model (OR = 2.56 [1.23–5.34]) but not after adjusting for duration of antiretroviral therapy (ART), CD4+ count, and other cardiovascular risk factors (OR = 0.94 [0.29–3.08])." (PMID 30481210, 2018). "We hypothesized that CD4+ cells and, in particular, the CD28 null cell subset could show a different degree of peripheral percentage in subjects with acute ischemic stroke in relation to clinical subtype and severity of ischemic stroke." (PMID 25997053, 2015). "Thus, we hypothesized that CD4+ cells and, in particular, the CD4+ CD28− subset could show a different degree of increased peripheral percentage in subjects with acute ischemic stroke in relation to clinical subtype and severity of ischemic stroke." (PMID 25997053, 2015). "We prospectively assessed circulating CD4+, CD8+, and double-negative T cells using flow cytometry in 52 patients on days 1, 3, 10, and 90 after ischemic stroke." (PMID 40342517, 2025).
head and neck cancer (58 papers, 2005 to 2026). A primary or metastatic malignant neoplasm affecting the head and neck. "For instance, the Bcl-2/Bax ratio was significantly associated with both the absolute number and the rate of CD4(+) T cells and natural killer cell activity in head and neck cancer patients." (PMID 33622179, 2021). "Contrary to the putative pro-tumorigenic effect, the presence of Foxp3+CD4+ T cells has been associated with a good prognosis in colorectal and head and neck cancers." (PMID 26604855, 2015). "Previous studies figured out that in head and neck cancers, photon radiotherapy significantly reduces peripheral CD4+ and CD8+ T lymphocyte counts post-treatment, with reductions typically ranging more than 50%." (PMID 40657253, 2025). "Another previous study revealed that the activated and resting T cells CD4 memory were enriched in head and neck cancer samples with high- and low-TMB, respectively, which is consistent with our results." (PMID 37100457, 2023). "In a model of head and neck cancer, ex vivo irradiation (10 Gy) of CD4+ T cells isolated from mouse spleen induced pSTAT‐3 expression correlated with increased Tregs and TGF‐β, suggesting radiotherapy mediated the conversion of CD4+ T cell to Tregs." (PMID 32994997, 2020). "Here, we report that the expression level of MMP25 correlated to the activated CD4+ memory T cells and prognosis in head and neck cancer." (PMID 32850314, 2020). "The TIMER database revealed that MMP25 expression was positively correlated with immune cells infiltration, including B cell, CD8+T cell, CD4+ T cell, and macrophage in head and neck cancers." (PMID 32850314, 2020). "The Kaplan–Meier method analysis of CIBERSORT data suggested that the infiltration level of activated memory CD4+ T cells was significantly related to the survival outcome of head and neck cancer patients." (PMID 32850314, 2020). "In summary, increased MMP25 expression correlates with better prognosis and increased immune infiltration levels in head and neck cancer, especially activated CD4+ memory T cells." (PMID 32850314, 2020). "This view fits with previous studies showing no or a positive prognostic effect of Foxp3+ Tregs in head and neck cancer, as here the number of co-infiltrating (activated) CD4+ and CD8+ T cells is also much higher than that of Tregs." (PMID 30658697, 2019). "The ability of cisplatin-based chemotherapy and radiation to decrease the numbers of CD4+T cells but to increase the percentage of CD4+CD39+ Tregs in head and neck cancer patients has been previously published." (PMID 28674498, 2017). "In patients with head and neck cancers, chemoradiotherapy also resulted in decreased frequency of circulating CD4+ T cells (p < 0.002) and increased Treg cells (p ≤ 0.001)." (PMID 27835886, 2016). "It has been reported that bortezomib, a first-generation proteasome inhibitor, could regulate the tumor microenvironment of head and neck cancer by recruiting tumor infiltrating immunocytes including CD4+/CD8+ T cells, B cells, macrophages and NK cells." (PMID 36386204, 2022). "The role of CD3 and CD4 in head and neck cancer has been less documented." (PMID 30153850, 2018). "Cetuximab, Immunoglobulin, Rituxan and Thymoglobulin are immune-related drugs encoded by FCGR3A and CD4 genes in which Cetuximab is an epidermal growth factor receptor (EGFR) inhibitor used for the treatment of metastatic colorectal cancer and head and neck cancer." (PMID 24564241, 2013). "After incubation of isolated naive CD4+ T cells in head and neck cancer milieu in vitro, we could detect a significant elevated number of Th17 cells." (PMID 20877351, 2010). "Three studies reported results for head and neck cancers without information on specific anatomical subsite; among them, the pooled HR was 0.77 (95% CI: 0.65–0.93), suggesting an inverse association between CD4+ and mortality." (PMID 33668519, 2021).
head and neck cancer (continued). "Interestingly, chemo-radiation has been shown to increase the proportion of CD4 + LAG-3+ expressing cells in head and neck cancer patients demonstrating that this effect may be clinically relevant and detectable." (PMID 32299365, 2020). "However, in a study of patients with head and neck carcinoma, those undergoing treatment with cisplatin or carboplatin along with fractionated radiation were found to have fewer CD4 and CD8 T cells in the blood than those untreated or receiving surgical treatment." (PMID 27532020, 2016). "In head and neck cancers, PD-1hi CD39+ CD4+ TILs exhibit terminal exhaustion but retain tumor antigen specificity and can be reactivated by PD-1 blockade." (PMID 41249701, 2025). "High expression levels of CCL22 and CCL17 are positively correlated with CD4+ T cell infiltration and a favorable prognosis with ICI treatment in patients with head and neck carcinoma." (PMID 38026978, 2023). "By secreting TGF and IL6, -SMA+ FAP+ CAFs in head and neck cancer suppress the growth of CD8+ T cells and increase the recruitment of CD4+ CD25+ T cells." (PMID 36465405, 2022). "A previous research comprehensively assessed the expression and prognosis of TNFAIPs family members in head and neck cancer and found a positive correlation between TNFAIP8 and tumor infiltrating immune cells macrophage, neutrophil, CD8+ T cell, CD4+ T cell, and dendritic cell)." (PMID 37210507, 2023). "Interestingly, administrating nivolumab and ISA101 by boosting antigen-specific CD4+/CD8+ T cells and elevating the efficacy of anti-PD-1 therapy has promising outcomes in human papillomavirus-related head and neck cancers." (PMID 36300095, 2022). "Our data indicate an enhanced influence of smoking and alcohol abuse on the dynamics and characteristics of circulating monocyte subsets and CD4/CD8 T-cell subset proportions, as well as an age-related weakened immunosuppression in head and neck cancer patients." (PMID 35625386, 2022). "Some studies suggested a negative prognostic value for high frequencies of tumor-infiltrating CD4+CD25+Foxp3+ Tregs in head and neck cancer, whereas others demonstrated a non-predictive or even positive prognostic role for these cells." (PMID 30658697, 2019). "Similar to the head and neck carcinoma literature, T regulatory cells were found to increase as a proportion of CD4 but did not increase in number due to the overall decrease in CD4 T cells." (PMID 27532020, 2016). "The hypothesis tested predicted that PBMC of these patients might be enriched in CD4+CD25+ Treg, which, by virtue of downregulating antitumour immune functions, could contribute to the progression or recurrence of head and neck cancer." (PMID 15714205, 2005). "Thus, the ratio of CD4+/CD8+ T cells decreased following SBRT (P = 0.017), which was also observed by Yang and colleagues in patients with head and neck cancer after receiving RT, although the radiosensitivities of CD4+ T and CD8+ T cells have been demonstrated to be similar." (PMID 32039000, 2019).